BRD4 (bromodomain containing 4)
Diseases named in the same sentence as BRD4 in open-access papers (continued):
Sharing a sentence is not in itself a finding about the gene and the disease.
acute myeloid leukemia (continued). "While we are investigating the interaction between BRD4 with wild-type and PCa-associated variants and its role in PCa cell invasion, it has been shown recently that wild-type ERG is acetylated by p300 and interacts with BRD4 to initiate gene transcription in acute myeloid leukemia (AML)." (PMID 27223260, 2016). "Moreover, a study using shRNA library targeting 243 known chromatin regulators identified Brd4 as a required factor for the maintenance of acute myeloid leukemia (AML)." (PMID 24592384, 2014). "In addition, Brd4 has also been considered a promising therapeutic target in acute myeloid leukemia (AML) because of its ability to sustain P-TEFb-dependent c-Myc expression." (PMID 25053741, 2014). "Recently, small molecular inhibitors of BRD4 have been identified and may hold promise for the treatment of cancer subtypes, including acute myeloid leukemia." (PMID 24874471, 2014). "It induces CRBN-dependent degradation of BET family proteins, including BRD2, BRD3, and BRD4, in human acute myeloid leukemia (AML) cells with a DC50 of 100 nM." (PMID 40507351, 2025). "Similarly, in acute myeloid leukemia, BRD4 has been shown to co-localize and synergistically interact with hematopoietic TFs (including PU.1, FLI1, ERG, C/EBPα, C/EBPβ, and MYB) combined with lysine acetyltransferase p300/CBP to support specific transcriptional circuits in this disease." (PMID 37446009, 2023). "In acute myeloid leukemia (AML), BRD4 has been reported to be critical for disease maintenance and suppression of BRD4 led to significant antileukemic effects in vitro and in vivo." (PMID 36733715, 2023). "dBET1 represents a proteolysis-targeting chimera (PROTAC) targeted against BET family members, and targeted BRD4 degradation in acute myeloid leukemia (AML) by dBET1 specifically impairs MYC transcription." (PMID 36969025, 2023). "It has been found that SRPK1 was a genetic vulnerability of acute myeloid leukemia (AML) through effects on isoform usage of epigenetic regulators including BRD4." (PMID 35846993, 2022). "By regulating the expression of transcription factor c-myc and Wnt5a, BRD4 is ascribed as a key determinant in acute myeloid leukemia (AML), multiple myeloma, Burkitt’s lymphoma, colon cancer, and inflammatory diseases." (PMID 35987950, 2022). "In acute myeloid leukemia (AML), acetylated histone H4 and hematopoietic transcription factors interact with BRD4 via a common KacGGKac motif to recruit BRD4 to regulatory sites." (PMID 34540900, 2021). "Two studies demonstrated that acute myeloid leukemia (AML) and multiple myeloma depend on the BRD4-MYC axis, and that pharmacological modulation of JQ1 inhibited cancer cell proliferation in vitro and in vivo." (PMID 31226848, 2019). "In contrast, high levels of H3K27ac marks were observed in a more distal 3′ region termed the BRD4-dependent MYC enhancer (BDME), which has been implicated in regulation of MYC in acute myeloid leukemia (AML) and in GSI-resistant cortical T-ALL." (PMID 27148573, 2015). "H3K27ac super-enhancer landscapes near MYC showed a pattern previously reported in acute myeloid leukemia (AML) that is sensitive to BRD4 inhibitors, and in line with this ETP-ALL blasts downregulated MYC in response to the BRD4 inhibitor JQ1." (PMID 27148573, 2015). "Specifically, BRD4 stands out in the BET family members as a particularly specific target for cancers such as Burkitt’s lymphoma, multiple myeloma (MM), and acute myeloid leukemia (AML)." (PMID 39274873, 2024). "Bromodomain‐containing protein 4 (BRD4) inhibitors have been clinically developed to treat acute myeloid leukemia (AML), but their application is limited by the possibility of drug resistance, which is reportedly associated with the activation of the WNT/β‐catenin pathway." (PMID 36567628, 2023). "In acute myeloid leukaemia (AML) cells, BRD4 was efficiently degraded after treatment with PROTAC 2 at a concentration of 100 nM." (PMID 35702740, 2022).
acute myeloid leukemia (continued). "Bromodomain-containing protein 4 (BRD4), the most famous member of the BET family, is overexpressed in acute myeloid leukemia (AML) cells and regulates the transcription of genes related to AML pathogenesis." (PMID 34149798, 2021). "In acute myeloid leukemia (AML) and myeloma, pre-clinical models and clinical trials already show the BRD4 inhibition induces strong suppression of tumor progression." (PMID 33299103, 2020). "Both JQ1 and PFI-1, another highly selective inhibitor of BRD4 and BRD2, also displayed significant antitumor activities in vivo in xenograft models of DLBCL, Burkitt’s lymphoma or acute myeloid leukemia and thereby improved survival of engrafted mice." (PMID 26654227, 2015). "NSD3 is involved in several varieties of cancers as it contributes to tumorigenesis by interacting with the bromodomain-containing protein 4 (BRD4) and the bromodomain and extra-terminal (BET) protein, which are potential therapeutic targets in acute myeloid leukemia." (PMID 38516186, 2024). "In addition, NEO2734 shows more potent anticancer effects than single-agent BRD4 or CBP/p300 inhibitors in lymphoma and acute myeloid leukemia cell lines, and exerts substantial anticancer effects in mouse models of lymphoma and acute myeloid leukemia." (PMID 38135679, 2023). "Fiskus and team found that co-treatment of BRD4 antagonist (JQ1) and HDAC inhibitor panobinostat showed promising results against human acute myeloid leukemia (AML) and the co-treatment was more effective in the induction of apoptosis than individual treatment with either of the inhibitors." (PMID 35408693, 2022). "Recently, many studies have found that inhibition of bromodomain-containing protein 4 (BRD4) with pharmacological BET-specific bromodomain (BD) inhibitors can effectively block MYC expression in multiple myeloma, acute myeloid leukemia, and Burkitt's lymphoma 27-29." (PMID 32929368, 2020). "CDK8-ChIPseq in the acute myeloid leukemia (AML) cell line of MOLM-14 cells (mixed lineage leukemia fusion MLL-AF9) has found CDK8 on super-enhancers (SE) paralleled by the binding of MED1 and BRD4." (PMID 31248103, 2019). "Cotreatment with the Brd4 inhibitor JQ1 and the HDAC inhibitor panobinostat synergistically induced apoptosis of human acute myelogenous leukemia (AML) blast progenitor cells (BPC) through attenuation of c-Myc and Bcl-2 expression, while increasing p21 and Bim expression." (PMID 26405162, 2015). "They identified numerous targets, including Bromodomain-containing Protein 4 (BRD4), Histone Methyltransferase DOT1L (DOT1L), and Multiple endocrine neoplasia type 1 (MEN1) for Acute Myeloid Leukemia (AML)." (PMID 38725484, 2024). "Importantly, the BRD4 BD2 domain inhibitor ABBV-744, which shows much less toxicity to normal tissues in preclinical models, has also entered a Phase I clinical trial in relapsed or refractory acute myeloid leukemia patients." (PMID 38135679, 2023). "These compounds have demonstrated impressive pre-clinical efficacy in a variety of cancer models, including BRD4–NUT fusions NUT-midline carcinoma (NMC), acute myeloid leukemia (AML), medulloblastoma, breast cancer, and lung cancer." (PMID 35745584, 2022). "Previously, we reported that sustained degradation of BRD4 led to downregulation of CD44, MYC, and CXCR4 in acute myeloid leukemia (AML) stem cells and improved survival in a mouse model of AML." (PMID 35173274, 2022). "In line with the function of NSD3-short as an adaptor protein of BRD4 and CHD8, MLL-AF9 rearranged acute myeloid leukemia (AML) were proven to be dependent on NSD3." (PMID 34440470, 2021). "The bromodomain and extra terminal (BET) family protein bromodomain containing protein 4 (BRD4) is an epigenetic regulator recently identified as a therapeutic target for several hematological cancers, notably mixed lineage leukemia-fusion acute myeloid leukemia (MLL-AML)." (PMID 24403256, 2013).
acute myeloid leukemia (continued). "An unanticipated powerful way for lowering Myc levels in haematopoietic cancers has emerged from the discovery that the incurable nature of MLL-AF9 acute myeloid leukaemia (AML) depends upon the presence of the not yet well understood protein bromodomain 4 (BRD4)." (PMID 23303309, 2013). "In addition, core binding factor acute myeloid leukemia (CBF-AML), nucleophosmin 1 (NPM1) and fms related receptor tyrosine kinase 3 (FLT3) in risk stratification have no impact on the expression of BRD4, PD-L1 and PD-1." (PMID 33658927, 2020).
nut midline carcinoma (86 papers, 2012 to 2026). A rare, highly aggressive and lethal carcinoma that affects children and young adults. "About 70% of NUT carcinoma is associated with chromosome translocation events that lead to the formation of a BRD4::NUTM1 fusion gene." (PMID 38724194, 2024). "Among NUT carcinoma, BRD4:NUTM1 was the most common variant and only one case harbored BRD3:NUTM1 rearrangement." (PMID 36937407, 2023). "NUT midline carcinoma (NMC) is caused by translocation-derived fusion proteins BRD4-NUT or BRD3-NUT." (PMID 36187481, 2022). "Phosphorylation of BRD4 (pBRD4) is often associated with enhanced BRD4 oncogenic activities in cancer, as demonstrated by hyper-phosphorylated BRD4 in NUT midline carcinoma, potentially mediated by CDK9." (PMID 34540900, 2021). "Chromosomal translocation of BRD4 to the locus encoding nuclear protein in testis (NUT) causes NUT midline carcinoma (NMC), a rare aggressive subtype of squamous cell carcinoma." (PMID 28525743, 2017). "Notably, a case report described an exceptional response to BMS-986158 (BETi) in a patient with BRD4-NUTM1 NUT carcinoma harboring a BRD4 splice-site mutation, highlighting the potential for personalized BET-targeted therapy." (PMID 41583469, 2025). "Importantly, BRD4 itself is a target of mutation in cancer: NUT (nuclear protein in testis) carcinoma (formerly known as NUT midline carcinoma) is characterized by the presence of NUT fusion oncogenes, the most common being BRD4-NUT." (PMID 33916219, 2021). "As an atypical activated domain, pathogenic enhancer bound by BRD4-NUT with hyper H3K27 acetylation signature in NUT midline carcinoma was reported to form “megadomains” raging from 100 kb to 2 Mb, although the presence of natural enhancers like this is still unknown." (PMID 34736895, 2021). "NUT midline carcinoma (NMC) is caused by a translocation-derived fusion protein, BRD4-NUT or BRD3-NUT, which hyperacetylates the nucleosomal domains including the anti-differentiation genes." (PMID 27827996, 2016). "NUT carcinoma (NC) is an aggressive solid tumor driven by the BRD4::NUTM1 and other NUTM1 fusion genes." (PMID 41266112, 2026). "NUT carcinoma (NC) is an aggressive and poorly differentiated squamous cell cancer driven by BRD4::NUTM1 and other NUTM1 fusion oncogenes." (PMID 41266112, 2026). "NUT carcinoma (NC) is an aggressive malignancy driven by BRD4::NUTM1 and other NUTM1 fusion oncogenes." (PMID 41266112, 2026). "Characterized by rearrangements of the NUTM1 gene, NUT carcinoma most commonly arises when the NUTM1 gene fuses to the BRD4 transcriptional activator." (PMID 41194824, 2025). "JQ1 has a strong antiproliferative effect against BRD4-dependent cancer cell lines and NUT midline carcinoma (NMC)." (PMID 40650308, 2025). "NUT carcinoma depends on the BRD4::NUTM1 fusion, which current inhibitors can target but without durable clinical efficacy." (PMID 41190236, 2025). "BRD4::NUTM1 has been shown to drive overexpression of SOX2 in NUT carcinoma cells, which induces an aberrant stem cell-like growth feature." (PMID 38315310, 2024). "For example, CDK9 inhibition can disrupt transcriptional elongation, resulting from BRD4-NUT fusion proteins in NUT midline carcinoma, leading to cancer cell apoptosis." (PMID 38172923, 2024). "BET inhibitors are currently used to treat patients with NUT midline carcinoma, driven by a BRD4-NUT fusion oncoprotein, and are a potential treatment avenue for tumors that have aberrant BET protein or gene function, such as ameloblastoma." (PMID 38594748, 2024). "The purpose of this study is to examine the potential impact of BRD4 PROTAC compounds ARV-825 on oncogene BRD4-NUT fused protein in NUT carcinoma." (PMID 38130463, 2023). "In NUT carcinoma, which is frequently caused by the fusion of the bromodomains of BRD3 or BRD4, the oncogenic characteristics of BET proteins were initially identified." (PMID 38130463, 2023).
nut midline carcinoma (continued). "The BRD4 inhibitor GSK525762 (Molibresib) has shown promising anticancer effects in a Phase I clinical trial in patients with NUT carcinoma." (PMID 38135679, 2023). "BRD4 consists of 5 proteins and most cases of NUT midline carcinoma involve translocation of the BRD4 with NUT genes." (PMID 36180820, 2022). "NUT midline carcinoma is characterized by NUT gene rearrangement with the BET bromodomain gene BRD4." (PMID 35836809, 2022). "BI 894999, CCS1477 or the combination of both were administered p.o. daily in three different NUT carcinoma xenograft models, two with BRD4-NUT fusion and one with BRD3-NUT fusion." (PMID 35444289, 2022). "The typical NUT carcinoma harbors BRD4, BRD3, NSD3, or Z4 bromodomain complex (BDC) protein genes as fusion partners to NUTM1 and manifests histologically as an undifferentiated to poorly differentiated carcinoma." (PMID 34997561, 2022). "The interference of JQ-1 induces immediate apoptosis in BRD4-dependent human carcinoma cells and reduces tumour growth of NUT midline carcinoma (NMC) in patient-derived xenograft models." (PMID 35702740, 2022). "Taken together, these investigations show that the fusion of NUT to BRD4 in NUT Carcinoma cells reconstitutes, in somatic cells, a functional loop, which normally drives histone hyperacetylation and chromatin binding by a BET factor in spermatogenic cells." (PMID 35565363, 2022). "Understanding the function of the oncogenic BRD4-NUT fusion protein in NUT carcinoma (NC) cells has proven to be essential in uncovering the mechanisms underlying histone hyperacetylation in spermatogenic cells." (PMID 35565363, 2022). "The function of NUTM1 fusion genes was primarily characterized in NUT carcinoma with BRD4-NUT fusion." (PMID 34898574, 2021). "Studies based on the prototype BETi JQ1 demonstrated that JQ1 replaces BRD4 from the chromosome and induces squamous differentiation and growth arrest in NUT carcinoma." (PMID 34898574, 2021). "NUT carcinoma is a rare, poorly differentiated carcinoma characterised by a genomic rearrangement of the nuclear protein of testis (NUT) gene, with BRD4-NUT being the most common fusion variant." (PMID 33351171, 2021). "NUT carcinoma with BRD4-NUT fusion was ultimately diagnosed using a NUT monoclonal antibody, fluorescence in situ hybridization, and RNA-seq." (PMID 33176817, 2020). "We describe here the first Brazilian case of NUT midline carcinoma with BRD4-NUT fusion detected in a next-generation sequencing panel and we present the clinical evolution of this patient." (PMID 31492174, 2019). "Bromodomain (BRD) and extra-terminal proteins (BET) inhibitors showed rapid antitumor activity in three patients with BRD4–NUT fusion NUT carcinoma." (PMID 28595655, 2017). "Mammalian BET proteins, most notably Brd4, have raised broad biomedical interest as well, because they can support several types of cancer, including NUT midline carcinoma, multiple myeloma and acute leukemia." (PMID 27233051, 2016). "The fusion protein BRD4-NUT is responsible for the aggressive NUT midline carcinoma, while interaction of BRD4 with acetylated NF-κB/RelA leads to constitutively active NF-κB, enhancing cancer cell proliferation." (PMID 25989842, 2015). "Recurrent gene fusions that characterize distinct subtypes of cancers include BRD4-NUT in NUT midline carcinoma, ETV6-NTRK3 in secretory breast carcinoma, CRTC-MAML2 fusions in mucoepidermoid carcinoma, and RAF family fusions in pilocytic astrocytomas." (PMID 26684754, 2015). "Of note, the related BET inhibitor I-BET76224 is currently in clinical trials for NUT midline carcinoma, an aggressive epithelial carcinoma characterized by genomic rearrangement of BRD4 or BRD3 (ClinicalTrials.gov identifier: NCT01587703)." (PMID 24220271, 2014).